TNF (tumor necrosis factor)
Diseases named in the same sentence as TNF in open-access papers (continued):
Sharing a sentence is not in itself a finding about the gene and the disease.
infection (continued). "Dural macrophages act as immune sentinels that phagocytose invading microbes, namely viruses, and release different cytokines, such as interferon-beta (IFN-β), -gamma (IFN-γ) and tumor necrosis factor (TNF), to recruit peripheral effector immune cells that are essential to resolve the infection." (PMID 37580702, 2023). "In addition, infection increased the concentration of TNF-α in the infected groups treated with testosterone and with letrozole + testosterone." (PMID 37384220, 2023). "Anti-TNF-α or anti-IL-17A Ab treatment suppressed the infection-induced upregulation of MMP-8." (PMID 37939119, 2023). "The reduced levels of early-response cytokines (IL-6, IL-1β, and TNF-α) following LDRT after infection on both day 1 and 3 were increased in the anti-TGF-β mAb-treated group, which was similar to the levels in virus-infected mice without LDRT (infection + mouse IgG group)." (PMID 37304302, 2023). "Notably, the levels of IL-1β, IL-6, and TNF-α were significantly elevated following infection with B1033 compared with those in the wild-type (p < 0.001)." (PMID 37998345, 2023). "This is of interest, as it has been reported that activation induced by TNFα protects the host cell against infection-induced apoptotic death and, thus, is critical for host cell survival but even with the low levels measured during the study, no clear signs of increased cell death were seen." (PMID 37085774, 2023). "Less is known about the contribution of LT and TNF to the organization of WP after STm infection." (PMID 36950118, 2023). "Prior studies of cytokines in blood have found that IL-6, IL-10, and TNF-α increase in burn compared to healthy pediatric patients, that elevated circulating TNF-α is associated with death, and that decreased circulating TNF-α/IL-10 ratio is correlated with an increased chance of infection." (PMID 36790939, 2023). "Furthermore, our results suggest that infection with single-stranded viruses will produce much greater microglial TNF release than bacterial infection." (PMID 34297254, 2022). "In addition, expression of pro‐inflammatory cytokines including IL‐6 and TNF was slightly downregulated upon infection while BCR‐signalling genes were significantly upregulated." (PMID 34169553, 2022). "Neuroinflammation is an inflammatory response which is induced by disease, stress, infection, or damage and mediated by cytokines such as Tumor Necrosis Factor alpha (TNFα), Interleukin (IL)-6, IL-1β, Interferon (IFN)γ and IL-8, chemokines, ROS, and secondary messengers." (PMID 36421455, 2022). "However, few responses were detected in the lung during the second infection, except the levels of TNF-α and MIP-1-α, which increased after reinfection." (PMID 35893674, 2022). "Then, assess the levels of NO, IL-6 and TNF-α in the culture medium 12 to 48 h after infection." (PMID 35324841, 2022). "Briefly, anti-TNF drugs may be more immunosuppressive than VDZ and UST and may have a higher risk of hematologic tumors and serious infections." (PMID 35160280, 2022). "Anti-TNFα is a mainstay therapy in IBD treatment; however, it may be associated with increased susceptibility to infections and a lower vaccine response." (PMID 35893835, 2022). "This surprising influence of TNF on macrophage polarization was confirmed in infection models." (PMID 36358688, 2022). "The release of tumor necrosis factor alpha (TNF-α) would also enhance the expression of E-selectin adhesion molecules on the endothelial cells, resulting in increased recruitment of monocytes to the site of infection." (PMID 36189361, 2022). "In response to infection and infection plus SP-A2 (1A0) protein rescue, a subset of the miRNAs, miRNA-mRNA targets, and genes identified with significant changes in their levels in male and female mice were involved in TNF and cell cycle signaling pathways." (PMID 35844510, 2022). "The TNF signaling, on the other hand, was present only in the infection group." (PMID 35844510, 2022).
infection (continued). "TNF-α is an acute-phase cytokine produced during the early stages of infection." (PMID 35335696, 2022). "Besides estrogen, treatment with proinflammatory cytokines such as interleukin 6 (IL-6) and tumor necrosis factor alpha (TNFα) and infection with RNA viruses also induce the upregulation of RNF115 in various cell lines and primary human and mouse cells." (PMID 35844553, 2022). "However, 5 days after infection, an inflammatory response associated with overexpression of IFN-γ and TNF-α in serum, and PD-1 expression on CD4+ T cells are significantly increased." (PMID 36093199, 2022). "Meanwhile, the highest values of TNF-α (> 50 pg/mL) were secreted only in four infections." (PMID 35531337, 2022). "Infection with SARS-CoV-2, a virus that has recently been linked to ALI and ARDS, has been linked to an inflammatory storm (marked by elevated levels of IL-6, IL-12, and IL-1, as well as TNF and deficient type I interferon activity)." (PMID 35813860, 2022). "Similarly, ESBL-EAEC infection elevated transcription levels of IL-1β, IL-6 and TNF-α in colonic tissues, but recovered after GA administration with an obvious decline of IL-10 and TGF-β." (PMID 35399688, 2022). "Interestingly, in the present work local levels of TNF were increased by infection in early pregnancy, time in which HO-1 overexpression and related pathological markers are observed, and decreased after HO-1 inhibitor treatment." (PMID 35619717, 2022). "The levels of inflammatory factors in the colon tissues of CRKP colonization-challenged mice were significantly higher than those in normal mice, with significantly enhanced TNF-α, IL-1β, and IL-6 expression, and translocated infection further enhanced the expression of IL-6." (PMID 36445086, 2022). "Moreover, upon infection of OKs by such co-incubated P. gingivalis, the mRNA levels of IL-8 and TNFα increased significantly more and for IL-8 this translated into increased protein levels when gingipains were inhibited." (PMID 35978839, 2022). "Two (miR-155 and miR-125b) of the three DE miRNAs that were unique to the ST12 infection are involved in the regulation of TNF production during mycobacterial infection and the ST12-induced miRNAs were associated with a stronger inflammatory response than the ST103." (PMID 36145441, 2022). "The AAV9-SLPI infection has significantly reduced inflammatory cytokine levels when compared with AAV9 group (TNF-α: 85.92 ± 36.24 ng/mg vs. 186.1 ± 12.17 ng/mg, p < 0.05, IL-1β: 29.48 ± 4.20 ng/mg vs. 69.03 ± 9.17 ng/mg, p < 0.05, and IL-6: 74.23 ± 10.50 ng/mg vs. 113.1 ± 28.43 ng/mg, p < 0.05)." (PMID 36061560, 2022). "Pro-inflammatory cytokines such as TNF-alpha and IL-6 are produced in response to infection." (PMID 35631351, 2022). "Indeed, during early lung infection with TIGR4 despite reduced BALF TNF levels, the levels of IL‐1β were increased compared to infection with TIGR4Δply." (PMID 35835695, 2022). "There was no significantly increased risk of infection in the first year of life even with use of anti-TNF in the third trimester." (PMID 36225722, 2022). "Although the pathogenesis of VU is likely multi-factorial, our results indicate that the increase of specific inflammatory mediators, such as IL-6, IL-10, IL17A, and TNF-α in wound fluids can be found in the presence of an infection particularly when sustained by biofilm-producing bacteria." (PMID 36140047, 2022). "However, during intestinal protozoan/P. falciparum infection, a significant reduction in pro-inflammatory cytokine levels (IL-6, TNF-α) was observed, suggesting that infection with G. duodenalis, E. histolytica, or Blastocystis sp." (PMID 35421083, 2022). "Secondary infection with B. canis resulted in significantly higher induction of CD4+ T lymphocytes in the lungs producing both IFN-γ and TNF-α while significant induction of trifunctional CD4+ T lymphocytes was noted during secondary infection with B. melitensis in the spleen." (PMID 36032120, 2022).
infection (continued). "Moreover, the TNFα gene was relatively highly expressed in intestinal lymph cells of sheep selected for resistance to nematodes during infection with Trichostrongylus colubriformis." (PMID 34979909, 2022). "The cytokine response to M. tb varies depending on the progression of the infection and whether it is active or latent, but it is well established that Th-1 cytokines, such as TNF-α and IFN-γ, are principally important for granuloma formation and maintenance." (PMID 35453358, 2022). "Protection against Mtb requires a distinctly defined type 1 response, mediated by interferon-gamma (IFNγ), IL-2, and tumor necrosis factor-alpha (TNFα), which may clear the infection or restrain it into an immune-mediated containment, also known as latency." (PMID 36006249, 2022). "However, this LPS-induced IL-12 and TNF-α secretion was progressively inhibited with increasing time of LDPm infection (maximum inhibition occurred at 24 h postinfection)." (PMID 35924848, 2022). "However, careful monitoring is warranted for specific OIs such as herpes zoster infection following JAKi treatment, mucocutaneous candidiasis following anti-IL-17 treatment, and Mycobacterium tuberculosis infection following anti-TNF treatment." (PMID 36278224, 2022). "For instance, increased periodontal pathogen abundance will enhance the stimulation of TLRs, induce Th1 to secrete IL-2, IFN-γ, TNF-α to kill intracellular infection pathogens, and then induce Th2 to secrete IL-4, IL-5, IL-6, IL-13 to regulate humoral immunity and limit Th1 response." (PMID 35254118, 2022). "In this study, we investigated expression of pro-inflammatory cytokine genes in epithelial cells infected with HAdV26 and found that HAdV26 infection of human epithelial cells triggers the expression of pro-inflammatory cytokines, namely IL-6, IL-8, IL-1β, and TNF-α." (PMID 35458402, 2022). "Infection and contact to worm antigens cause a weak transient Th1 response to occur which is characterized by the production of interferon-γ (IFN-γ) and tumor necrosis factor-α (TNF-α), among other signaling proteins." (PMID 36505463, 2022). "Reduced TNF-α contributes to a more persistent intracellular infection in the hosts." (PMID 35651754, 2022). "The observed higher expression of TNF-α gene in the present study may indicate the resistance of fish to infection." (PMID 36118353, 2022). "Taken together, these results suggest that the host SUMOylation process favors the infection and survival of L. donovani in macrophages by modulating the levels of pro-inflammatory cytokines such as TNF-α, IFN-γ, IL-12p40, and IL-32γ and anti-inflammatory cytokine, IL-10." (PMID 35734580, 2022). "For instance, ST infection could recruit the inflammatory monocytes to the CNS in mice; Salmonella-derived LPS markedly activated the expression of TNF-α, IL-1β, and IL-6 in microglia and astrocytes in vitro." (PMID 35967771, 2022). "TNF production was observed in a dose-dependent manner after stimulation with E. tenella sporozoites and merozoites in chicken macrophage cells after primary infection." (PMID 35214673, 2022). "The TNF-α gene was upregulated at 6 and 12 hours and downregulated at 24 and 48 hours after infection in the planktonic group; in the biofilm group, it was downregulated at 6, 12, 24, and 48 hours after infection." (PMID 35677656, 2022). "Altogether, TNF-α elicited RIP1/FADD/caspase-8-mediated apoptosis of astrocytes upon AC infection." (PMID 33683530, 2022). "Moreover, HDAC6 inhibition increased the release of pro-inflammatory cytokines (TNF and IL-12) upon infection with other bacteria, e.g. Mycobacterium tuberculosis." (PMID 36131943, 2022). "Thus, IL-1β and TNF-α, as stress-inducible genes, are consistently upregulated in expression during infection." (PMID 36139883, 2022).
infection (continued). "Pretreatment with TNFα was sufficient to restrict AD169 and TB40/e infection in MRC5 and ARPE19 cell types, respectively, and restricting glycolysis with 2DG during TNFα pretreatment largely restored the ability of HCMV to initiate infection as in our original model with AD169 and HFFs." (PMID 35834576, 2022). "Therefore, physicians should be careful about recurrent infections in patients under anti-tumor necrosis factor agents." (PMID 37274971, 2022). "This contrasted with DENV, where only IL-6 exhibited a strong correlation with [18F]FDG PET signals in the spleen (ρ = 0.72; CI: 0.38–0.89; p = 0.0007), despite IL-6 and TNF-α having more exaggerated expression in DENV spleens relative to ZIKV (8–14-fold higher than pre-infection)." (PMID 35876869, 2022). "Studies have shown that adjuvant YPFG therapy can improve the overall clinical response rate, increase serum immunoglobulin IgA, IgM, and IgG levels, and significantly decrease TNF-α levels, thereby reducing the rate of infection recurrence and improving children's immunity." (PMID 36619520, 2022). "TNF-α and IL-1β act through specific cell membrane-bound receptors and participate in the recruitment of polymorphonuclear neutrophils (PMNs) into the site of infection and their activation." (PMID 35614947, 2022). "However, the cell type in the mouse brain that secreted TNF-α to promote necroptosis of neurons upon AC infection was still unclear." (PMID 33683530, 2022). "Similarly, E. coli 1587 infection elevated the transcription levels of IL-1β, IL-6, TNF-α, and IL-10 in the colonic tissues, while TGF-β was decreased." (PMID 35643532, 2022). "Notably, we found that the levels of IL‐1β and TNF‐α in the serum and lung were substantially reduced at 12 h, and even at 16 h, 24 h, and 32 h post PmCQ2 infection by melatonin injection." (PMID 35184395, 2022). "Furthermore, the expression of Smh1 led to reduced induction of IL-8, IL-6 and TNFα transcript upon infection, which was also observed to a weaker extent in uninfected cells." (PMID 36411449, 2022). "NK cells eliminate target cells through direct cell-to-cell contact-based NK cell cytotoxicity (NKCC) and by secreting cytokines, such as interferon gamma (INF-γ) or tumor necrosis factor alpha (TNF-α), which recruit additional immune cells to the site of infection or inflammation." (PMID 35326467, 2022). "Other studies have found that in germ-free zebrafish, Lactobacillus casei BL23 in could effectively promote the expression of pro-inflammatory factors such as TNF-α, IL-10 and IL-1β to fight the infection with Aeromonas veronii." (PMID 35700135, 2022). "Interleukin (IL)-10, indoleamine 2,3-dioxygenase, and prostaglandin-E2 are secreted in early pregnancy to prevent maternal T-cell activation, and superoxide radicals and tumor necrosis factor (TNF)-α are secreted in late pregnancy to protect the fetus against infection and prevent preterm labor." (PMID 36402996, 2022). "Also, the quick production of TNF-α in the group vaccinated with fusion protein, in the first hours of infection has been predictive of better infection outcomes, including less tissue damage and better survival in mice." (PMID 36477013, 2022). "Synergistically to IFN-γ, TNF-α activates macrophages with a microbicidal profile and results in the destruction of intracellular forms of the parasite; thus, it acts in the control of infection." (PMID 35069009, 2022). "However, PMΦ from both strains of mice displayed decreased levels of NO, TNF-α, and IL-10 after 30 days of infection compared to the initial days of infection (7 days post-infection)." (PMID 36520787, 2022). "GABA treatment significantly mitigated TNFα production following infection (p<0.001)." (PMID 36389819, 2022). "The AUC in the whole blood TNF-a pre-US was 0.86 (Mann-Whitney U-test, p=0.003), which indicates that the whole blood LPS assay pre-US itself without any ultrasound intervention has high sensitivity and specificity for the diagnosis of infection." (PMID 35784337, 2022).
infection (continued). "Blockade of LFA-1 and VLA-4 in the coculture infection model resulted in 65.4%–96.2% (median 85.2%) inhibition of HIVIIIB and 78.1%–96.9% (median 93.4%) inhibition of HIVBaL infection of rCD4s cocultured with TNFα-treated HUVECs (p = .0002 and p = .0017, respectively)." (PMID 34465136, 2022). "Similarly, E. coli 1587 infection stimulated upregulation of IL-1β, IL-6, IL-10, and TNF-α mRNA transcription levels in mouse colons at 3 dpi, but this phenomenon mostly diminished in 7 dpi except for IL-6." (PMID 35643532, 2022). "IFNγ, IP-10 and IL-2 responses were strongly elevated in individuals with prior C. burnetii antigen exposure, whether through infection or vaccination, while IL-1β, IL-6 and TNFα responses were slightly increased in naturally exposed individuals only." (PMID 35812430, 2022). "Notably, mice infected with strain 1457 contained at this late stage of infection still more than twice as much of TNF-α in the infected tissue as mice infected with the isogenic ΔspoVG mutant." (PMID 35328675, 2022). "We examined the expression of IL-1β, IL-6 and TNF-α after infection with S. aureus." (PMID 35624447, 2022). "Moreover, in a related mouse model, in which infection is initiated at E0.5, antibody-mediated ablation of TNF resulted in midgestational rescue from PccAS-induced abortion." (PMID 35312688, 2022). "The levels of TNFα show a tendency to increase with infection in both strains." (PMID 35787830, 2022). "Thus, TNF and infection together activate cellular glutamine uptake and the resultant increase in glutaminolysis is the specific source of the increased succinate." (PMID 35737799, 2022). "In a murine model of infection, M. tuberculosis-induced potentiation of type 1 immune responses has been associated with protection against lethal malaria, which also appears to be related to induced production of IFN-γ and TNF-α in C57/BL6 mice." (PMID 36504775, 2022). "Moreover, partially inhibiting FBXW7 in Mm-infected mice not only decreased TNF-α production in vivo but also markedly relieved infection-related tissue damage." (PMID 35651754, 2022). "Blockade of TNF-α can provide protection against severe lung injury induced by lethal IV infection." (PMID 36180831, 2022). "These authors reported tilmicosin decreased intracellular infection (p < 0.01), had a protection effect on the mammary epithelial cells reducing apoptosis after infection by 80% (p < 0.01), reduced reactive oxygen species (p < 0.01), IL-1β (p < 0.01), IL-6 (p < 0.01) and TNF-α (p < 0.05)." (PMID 36557690, 2022). "Thus, the analysis of DEGs using GO and KEGG enrichment assays indicated a likely role of the HtrA protease in the TNF-α response to infection with H. pylori." (PMID 37193047, 2022). "In our study, the percentage of IFN-γ+TNF-α+ mCD4+ T cells significantly decreased at 7–12 months compared with that at 1–6 months post vaccination and returned to levels consistent with those of the infection-only group 7–12 months post vaccination." (PMID 36494338, 2022). "We carried out a systematic review to evaluate the incidence of infections and skin manifestations after anti-TNF-α de-escalation, irrespective of underlying inflammatory conditions." (PMID 35625771, 2022). "In addition to TNF-α, CXCL10 (one of the top five hub genes), and CCL5, two chemokines also found to be the hallmarks of the inflammation caused by LgyLRV1+ infection were also found to be present in the 8h_bisque4." (PMID 35992159, 2022). "Moreover, in the PCLS infection model, Pla plays a vital role for the inhibition of the expression of the proinflammatory cytokines IL‐6, IL‐8, and TNFα during the first hours of infection." (PMID 34570407, 2022). "While IL-1β and TNF-α levels may drop within 24–48 h, elevated IL-6 levels persist for a longer period over the course of the infection." (PMID 35888173, 2022).